PGAM4 (phosphoglycerate mutase family member 4)
Description:
May catalyze the interconversion of 2-phosphoglycerate and 3-phosphoglycerate, a crucial step in glycolysis, by using 2,3-bisphosphoglycerate. May also catalyze the interconversion of (2R)-2,3-bisphosphoglycerate and (2R)-3-phospho-glyceroyl phosphate.
Synonyms: PGAM3; dJ1000K24.1; PGAM-B; PGAM1
Tractability: PROTAC: ubiquitination databases record sites on it.
Gene: Protein-coding gene on chromosome X (77,967,949 to 77,969,638, reverse strand). Ensembl gene ENSG00000226784.
Subcellular location (Human Protein Atlas): Nucleoplasm; Mid piece
Gene Ontology:
Molecular function: phosphoglycerate mutase activity; bisphosphoglycerate mutase activity; catalytic activity; intramolecular phosphotransferase activity
Biological process: glycolytic process; positive regulation of flagellated sperm motility
Cellular component: extracellular exosome; sperm principal piece
Homologues: Orthologues: chimpanzee PGAM1 (96% identical), mouse Pgam1 (95% identical), rat Pgam1 (95% identical), zebrafish pgam1b (87% identical), zebrafish pgam1a (87% identical), tropical clawed frog pgam1 (84% identical), Drosophila melanogaster Pglym78 (66% identical), Drosophila melanogaster Pglym87 (60% identical). Paralogues in human: PGAM1 (96% identical), PGAM2 (78% identical), BPGM (52% identical).
Diseases named in the same sentence as PGAM4 in open-access papers:
PGAM4 is named in the same sentence as 11 diseases in open-access papers, as found by Europe PMC text mining. Sharing a sentence is not in itself a finding about the gene and the disease. The quoted sentences say what the papers report.
glioma (2 papers, 2023 to 2025). A benign or malignant brain and spinal cord tumor that arises from glial cells (astrocytes, oligodendrocytes, ependymal cells). "Recent studies have also highlighted the role of acetylation in regulating endothelial cell response to mechanical stress, glycolytic regulation in glioma cells through PGAM4." (PMID 40616587, 2025). "Recent studies in glioma cells have shown that acetylation‐regulated metabolic enzymes, such as PGAM4, play key roles in modulating glycolytic flux and chemoresistance, reinforcing the notion that lysine acetylation can act as a fine‐tuning mechanism in metabolic control." (PMID 40616587, 2025). "Despite a lack of study in lung cancer, PGAM4 is expected to promote tumor growth, such as in glioma." (PMID 37667226, 2023).
infertile (2 papers, 2012 to 2019). "We investigated whether there might be any PGAM4 genetic variants affecting male fertility by performing a case-control study of fertile and infertile men." (PMID 22590500, 2012). "We propose that PGAM4 contributes to reduced sperm motility, and thus infertility, by impairing glycolytic capacity." (PMID 22590500, 2012). "Moreover, PGAM4 can escape from MSCI, while the G75C SNP causes impaired enzymatic activity, leading to infertility in some men." (PMID 22590500, 2012).
lung adenocarcinoma (1 paper, 2023). A carcinoma that arises from the lung and is characterized by the presence of malignant glandular epithelial cells. "We found that high expression levels of PGAM1 and PGAM4 in lung adenocarcinoma (LUAD) patients and NOL6 in lung squamous cell carcinoma (LUSC) patients were associated with low overall survival rates." (PMID 37667226, 2023).
lung carcinoma (1 paper, 2023). "Although PGAM4 and NOL6 have not been actively studied in lung cancer, they are known to promote cell proliferation in other cancers." (PMID 37667226, 2023). "However, further experimental evidence is needed; for example, the roles of PGAM4 and NOL6 have not been studied in lung cancer." (PMID 37667226, 2023).
male infertility (1 paper, 2012). The inability of the male to effect fertilization of an ovum after a specified period of unprotected intercourse. "Using RT-PCR and western blot analyses, we identified that PGAM4 is a functional retrogene that is expressed predominantly in the testes and is associated with male infertility." (PMID 22590500, 2012).
pancreatic cancer (1 paper, 2023). "Based on survival analysis, 6 out of 32 MMRGs (LDHA, ALDH3B1, LDHAL6B, PKM, ALDH3A1, and PGAM4) in pancreatic cancer were of survival significance." (PMID 36814901, 2023).
cancer (4 papers, 2020 to 2025). A tumor composed of atypical neoplastic, often pleomorphic cells that invade other tissues. "PGAM1, PGAM4, and NOL6 have been reported to be tumorigenic in several cancers." (PMID 37667226, 2023).
tumor (2 papers, 2020 to 2023). "Furthermore, tumours without KRAS gene mutation show overexpression of ALDOB and CPS1 and downregulation of PGAM4 genes, which are involved in metabolic pathways such as biosynthesis of amino acids, gluconeogenesis, glycolysis and carbon metabolism." (PMID 31949199, 2020).
PGAM4 also shares sentences with these, for which no sentence is quoted: lung squamous cell carcinoma (1 paper); Pituitary adenoma (1); Stroke (1).